CD99 (CD99 molecule (Xg blood group))
Diseases named in the same sentence as CD99 in open-access papers (continued):
Sharing a sentence is not in itself a finding about the gene and the disease.
atherosclerosis (1 paper, 2018). A disease characterized by the build-up of fatty material and calcium deposition in the arterial wall resulting in partial or complete occlusion of the arterial lumen. "In atherosclerosis other groups have targeted DNA vaccines to vascular endothelial growth factor receptor 2 (VEGFR2), TIE2 (an endothelial marker), and CD99 a leukocyte and endothelial antigen resulting in significantly reduced atherosclerosis and leukocyte infiltration in ApoE-/- mice." (PMID 29641559, 2018).
autism spectrum disorder (1 paper, 2013). A spectrum of developmental disorders that includes autism, and Asperger syndrome. "We found that JARID2 and CD99 in our subnetwork and previous study have shown JARID2 functions together with CD99 in controlling autism spectrum disorder." (PMID 24328032, 2013).
carcinoid tumor (1 paper, 2009). A slow growing neuroendocrine tumor, composed of uniform, round, or polygonal cells having monotonous, centrally located nuclei and small nucleoli, infrequent mitoses, and no necrosis. "The carcinoid tumor component was strongly positive for CD56, chromogranin and synaptophysin, weakly positive for pancytokeratin, and negative for carbonic anhydrase IX, CD99, CDX2, cytokeratin 7, cytokeratin 20 and smooth muscle actin." (PMID 19523243, 2009). "The carcinoid tumor component was strongly and diffusely immunoreactive (3+, cytoplasmic staining) for CD56, chromogranin and synaptophysin; weakly and focally immunoreactive (1+, cytoplasmic staining) for pancytokeratin; and negative for CA-IX, CD99, CDX2, CK7, CK20 and SMA." (PMID 19523243, 2009).
cervical neoplasms (1 paper, 2021). "Although the origin of cervical PNET is not clear, the immunohistochemical markers of cervical neoplasms in this case, including CD99, Syn, CD56, and vimentin (partial), were positively expressed, which satisfies the diagnostic criteria of pPNET." (PMID 34006225, 2021).
cholangiocarcinoma (1 paper, 2023). A carcinoma that arises from the intrahepatic biliary tree (intrahepatic cholangiocarcinoma) or from the junction, or adjacent to the junction, of the right and left hepatic ducts (hilar cholangiocarcinoma). "We performed survival analysis on TCGA cholangiocarcinoma (CHOL) patients based on FN1 and CD99 expression." (PMID 38239853, 2023). "Therefore, CD99 does not appear to function merely as a cancer stem cell marker, but also influences cholangiocarcinoma cell communication with the fibroblast and tumor microenvironment." (PMID 38239853, 2023).
chronic atrophic gastritis (1 paper, 2023). Atrophic gastritis that is persistent and long-standing. "Through cell communication analysis, we have discovered that the CD99 signaling pathway network and the CDH signaling pathway network are the main communication pathways that significantly alter the microenvironment of gastric tissue during the development of chronic atrophic gastritis." (PMID 37608794, 2023).
clear cell carcinomas (1 paper, 2021). "By global mRNA microarray profiling in a total of 196 epithelial OC patients (161 serous, 15 endometrioid, 11 mucinous, and 9 clear cell carcinomas), we found four candidates—HSPA1A, CD99, RAB3A and POM121L9P, which associated with OS and poor clinicopathological features." (PMID 33686173, 2021).
colon carcinoma (1 paper, 2019). "We also investigated if tumor growth of the CD99 low CT26 colon carcinoma could be inhibited after vaccination against CD99." (PMID 31001265, 2019).
colorectal adenocarcinoma (1 paper, 2017). The most common type of colorectal carcinoma. "We used a human colorectal adenocarcinoma cell line (COLO 320) with high endogenous expression of meprin β to rule out the possibility that differences in CD99 cleavage were merely an artifact of meprin β overexpression." (PMID 28903388, 2017).
cutaneous melanoma (1 paper, 2011). A primary melanoma arising from atypical melanocytes in the skin. "In our patient's, history of cutaneous melanoma, the absence of cystic teratomas lesion and tumor positive stain for PS100 and Melan A markers and negative stain for of alpha-inhibin and CD99 confirmed the diagnosis of metastatic ovarian melanoma." (PMID 21682901, 2011).
cyst (1 paper, 2009). A sac-like closed membranous structure that may be empty or contain fluid or amorphous material. "Additionally, the teratomatous cyst wall showed strong staining for smooth muscle actin, and weak staining for carbonic anhydrase IX, CD99, chromogranin and synaptophysin." (PMID 19523243, 2009). "Additionally, the teratomatous cyst wall was strongly and diffusely immunoreactive (3+, cytoplasmic staining) for smooth muscle actin (SMA); and weakly and focally immunoreactive (1+, cytoplasmic staining) for carbonic anhydrase IX (CA-IX), CD99, chromogranin and synaptophysin." (PMID 19523243, 2009).
dementia (1 paper, 2025). Loss of intellectual abilities interfering with an individual's social and occupational functions. "Conversely, AD females lacked meaningful communication signals of CD99 compared to AD males, due to a significant reduction in this cell communication pathway among females with AD dementia." (PMID 41457042, 2025).
dermal neoplasm (1 paper, 2024). "The histopathological examination revealed a rather well-circumscribed dermal neoplasm extending into subcutaneous tissue with high mitotic activity and immunohistochemical positivity for vimentin, CD99, and Bcl-2, but not for markers like CD45, HMB45, and S-100." (PMID 39022482, 2024).
desmoplastic small round cell tumor (1 paper, 2025). Desmoplastic small round cell tumor (DSRCT) is an aggressive soft tissue cancer that typically arises in serous lined surfaces of the abdominal or pelvic peritoneum, and spreads to the omentum, lymph nodes and hematogenously disseminates especially to the liver. "However, despite its high sensitivity, CD99 is not entirely specific, as it is also expressed in a wide range of malignancies, including small round blue cell tumors like Ewing sarcoma, desmoplastic small round cell tumors (DSRCT), CIC-rearranged sarcomas, and BCOR-altered neoplasms." (PMID 40307756, 2025).
diffuse large B-cell lymphoma (1 paper, 2024). "One patient had diffuse large B-cell lymphoma, three patients had T-cell acute lymphoblastic lymphoma with immunohistochemistry showing Tdt (strong nuclear positive), CD3, CD10, CD20, and CD99 positivity, and Ki67 of up to 80%." (PMID 39350842, 2024).
embryonal rhabdomyosarcoma (1 paper, 2017). A poorly circumscribed morphologic variant of rhabdomyosarcoma. "Immunohistochemical stains were positive for vimentin, CD99, myogenin, and MyoD1 consistent with a diagnosis of embryonal rhabdomyosarcoma, botryoid subtype." (PMID 29375950, 2017).
experimental autoimmune encephalomyelitis (1 paper, 2024). An autoimmune demyelinating disease of the central nervous system that is produced experimentally in animals by the injection of homogenized brain or spinal cord in Freund's adjuvant. "By contrast, both sexes had similar CD99 expression in mice and Cd99-deficient mice showed equal susceptibility to experimental autoimmune encephalomyelitis compared to wildtypes." (PMID 38750588, 2024).
Fibrous Tumor (1 paper, 2014). "After a tumor resection, microscopic findings were spindled tumor cells with reactivity to CD34, bcl-2 and CD99 and the tumor was diagnosed as Solitary Fibrous Tumor." (PMID 25136435, 2014).
Glucose intolerance (1 paper, 2023). Glucose intolerance (GI) can be defined as dysglycemia that comprises both prediabetes and diabetes. "We also evaluated predicted signaling from myofibroblast and preadipocytes to IMs, which showed increased MHC-II, CD99, MIF, periostin, amyloid beta precursor protein (APP), and CSF signaling pathways with glucose intolerance and have been implicated in macrophage polarization." (PMID 37711619, 2023).
hamartoma (1 paper, 2015). A benign and excessive tumor-like growth of mature cells and normal tissues which grow in a disorganized pattern. "Thus, immunohistochemical detection of CD34, CD99, and bcl-2 is inefficient in differentiation of hamartoma-like SFTs from pancreatic hamartomas." (PMID 26425382, 2015).
hepatoblastoma (1 paper, 2021). Hepatoblastoma (HB) is a malignant hepatic tumor and is the most common pediatric liver cancer. "The other hepatoblastoma tumor showed positivity for CD10, CD9, CD81, CD105 in the absence of GD2, EpCAM, CD99, numyogenin, and CD90." (PMID 34638431, 2021).
kidney stones (1 paper, 2020). "The present study was designed to ascertain whether FURS for the treatment of kidney stones results in changes to neutrophils and monocytes cell surface expression of the CD62L, CD11b and CD99 adhesion molecules, and to assess the intracellular production of H2O2." (PMID 33308282, 2020). "The results are expressed as Mean Fluorescent Intensity (MFI) and represent changes to the CD99 cellular surface expression in both monocytes and neutrophils, both pre-operatively (baseline) and after FURS (30, 120 and 240 min post-operatively), for the treatment of kidney stones." (PMID 33308282, 2020).
Klippel-Feil syndrome (1 paper, 2020). A congenital, musculoskeletal condition characterized by the fusion of at least two vertebrae of the neck. "We demonstrate that two GDF6 prodomain mutants linked to Klippel-Feil syndrome are hyperactive in CD99-Src signaling." (PMID 33147457, 2020).
Lewis lung carcinoma (1 paper, 2021). "Meprin β was shown to shed the adhesion molecule CD99, thereby promoting the transendothelial cell migration (TEM) of Lewis lung carcinoma (LLC) cells." (PMID 34692768, 2021).
Leydig cell tumor (1 paper, 2025). A sex cord-stromal tumor occurring in the testis and rarely in the ovary. "The immunohistochemical analysis showed that the Leydig cell tumor was positive for calretinin and inhibin (alpha subunit), Sertoli cells were positive for CD-99, and GCNIS was positive for placental alkaline phosphatase and OCT-4." (PMID 40313596, 2025).
lipoblastoma (1 paper, 2020). A lipoma usually occurring in the extremities of young children (usually boys). "Tumors in which no fusion genes were detected included (CD99 negative) undifferentiated round cell sarcomas, tenosynovial giant cell tumors, and lipoblastomas." (PMID 31965673, 2020).
malignant kidney neoplasms (1 paper, 2021). "Tumor cells from all 17 malignant kidney neoplasms studied showed expression of CD271+ and CD81hi, together with positivity for EpCAM in the majority (12/17) of tumors (70%) and CD90 in 5/17 (29%), while they systematically lacked CD57, CD58, CD99, CD117, nuMyoD1, and numyogenin expression." (PMID 34638431, 2021).
Merkel cell tumors (1 paper, 2004). "CD 99 positivity suggests PNET; however, one series found CD99 to be positive in 40% of Merkel cell tumors." (PMID 15550173, 2004).
metastatic melanoma (1 paper, 2024). A melanoma that has spread from its primary site to another anatomic site. "In this respect, rare cases of dedifferentiated metastatic melanomas with CD99 have also been reported, highlighting the extraordinary heterogeneity of these neoplasms." (PMID 39001214, 2024).
myxofibrosarcoma (1 paper, 2023). A malignant fibroblastic neoplasm arising from the soft tissue. "In terms of immunohistochemistry, low-grade myxofibrosarcoma was positive for MUC4, BCL-2, CD99, and vimentin." (PMID 37189471, 2023).
neuroepithelial tumors (1 paper, 2023). "The histopathological review demonstrated a morphologically heterogeneous group of high-grade neuroepithelial tumors with positive immunostaining for markers of glial differentiation in combination with weak and focal expression of synaptophysin, CD56 and CD99." (PMID 36964296, 2023).
neurofibroma (1 paper, 2022). An intraneural or extraneural neoplasm arising from nerve tissues and neural sheaths. "Immunohistochemistry is positive for CD34 and CD99, more variably for EMA, and are always negative for S100, distinguishing it from neurofibroma, which is the most common pathological differential diagnosis." (PMID 36092267, 2022).
oncocytoma (1 paper, 2022). "Immunohistochemical examination revealed negative staining with vimentin (typical pattern characteristic for oncocytoma), whereas FLI 1 and CD99 were negative." (PMID 35276058, 2022).
Peripheral PNETs (1 paper, 2025). "Peripheral PNETs (pPNETs) typically express CD99, while central PNETs (cPNETs) do not." (PMID 41477273, 2025).
peritonitis (1 paper, 2023). Inflammation of the peritoneum (tissue that lines the abdominal wall and covers most of the organs in the abdomen). "Since anti-CD99 antibody substantially inhibited the migration of both neutrophils and monocytes in thioglycolate-induced peritonitis, decrease in CD99 expression might be another factor responsible for impaired neutrophil and monocyte recruitment in Iripin-1-treated mice." (PMID 36756125, 2023).
pheochromocytoma (1 paper, 2021). "The only pheochromocytoma analyzed (n = 1) showed a distinct CD56++ CD57+ GD2++ CD271+ CD9+ CD81+ CD90het CD58+ phenotype, in the absence of expression of CD10, CD99, CD117, EpCAM, nuMyoD1, and numyogenin." (PMID 34638431, 2021).
primitive neuroectodermal tumours (1 paper, 2015). "In younger patients, it could also be relevant to exclude the possible diagnosis of primitive neuroectodermal tumour by IHC staining for CD99, which is negative in pancreatic PDEC and positive in primitive neuroectodermal tumours." (PMID 26854147, 2015).
prostate tumor (1 paper, 2008). "Both PC3/Luc and DU145 cells were specifically stained by NKp30-Ig and NKp46D2-Ig, but not by the control CD99-Ig (grey histograms), thus indicating the expression of ligands for these two NK activating receptors on prostate tumor cell lines." (PMID 18478075, 2008).
psoriasis (1 paper, 2024). An autoimmune condition characterized by red, well-delineated plaques with silvery scales that are usually on the extensor surfaces and scalp. "In contrast, B-cells, primarily utilizing CD99, are prevalent in psoriasis, indicating a convergence of signaling pathways between these two immune cell types, potentially facilitating effective transmission and feedback of immune signals." (PMID 38289616, 2024).
retinal degeneration (1 paper, 2022). Degeneration of the retina. "Because nucleated cells found in peripheral circulation are mainly composed of leukocytes with reduced expression of CD99, a protein essential for leukocytes adhesion, translocation, and function, mLOY in these cells likely affect retinal degeneration through altered immunological surveillance." (PMID 35642040, 2022).
rhabdoid tumor (1 paper, 2022). An aggressive malignant embryonal neoplasm usually occurring during childhood. "CD99, OCT4, and OPN were well-expressed in all the rhabdoid tumor cell lines and HEK293." (PMID 35954348, 2022).
schizophrenia (1 paper, 2024). A major psychotic disorder characterized by abnormalities in the perception or expression of reality. "When we compared the full set of female and male schizophrenia DEGs across brain regions, we found an additional three overlapping genes (CD99, GABARAPL1, and LIN7B) shared with the caudate nucleus." (PMID 38730231, 2024).
Sepsis (1 paper, 2025). Sepsis is defined as life-threatening organ dysfunction caused by a dysregulated host response to infection. "Similarly, the ANXA1–FPR1/2 axis and CD99–CD99 or CD99–PILRA signaling were specifically enhanced in sepsis, all of which are closely associated with cell migration, immunosuppression, and the regulation of adhesion molecules." (PMID 41346577, 2025).
Sertoli cell tumor (1 paper, 2022). A sex cord-stromal tumor of the testis or the ovary. "Although CD99, calretinin, and AE1/3 are frequently expressed in Sertoli cell tumors, they are less specific and not as helpful in differential diagnosis." (PMID 36422177, 2022).
sex cord-stromal tumor (1 paper, 2012). A neoplasm involving a sex cord. "Sex cord-stromal tumors should be included in the differential diagnosis of retroperitoneal mass with ascites, and a panel of immunohistochemical markers such as calretinin, CD99, and inhibin can be used as an adjunct diagnostic tool." (PMID 22928131, 2012).
spindle cell rhabdomyosarcoma (1 paper, 2021). An uncommon variant of rhabdomyosarcoma characterized by the presence of whorls of spindle cells forming a storiform pattern. "Immunohistochemical analysis showed negative staining with Cytokeratin, S100, CD34, Stat6, h-Caldesmon and EMA while the tumour cells were positive for desmin, myogenin, smooth muscle actin, CD-99 and MyoD1 thus confirming the diagnosis of spindle cell rhabdomyosarcoma." (PMID 34104191, 2021).
Stroke (1 paper, 2021). Sudden impairment of blood flow to a part of the brain due to occlusion or rupture of an artery to the brain. "LAMA2, MLL4 and PLXDC2 are specifically expressed in (pre-)diabetic sera; CD99 is expressed in the sera of both healthy and (pre-)diabetic patients; and CD14, CLU and SAA2 are expressed in the sera of healthy, (pre-)diabetic and stroke subjects." (PMID 33995275, 2021).
systemic lupus erythematosus (1 paper, 2020). An autoimmune multi-organ disease typically associated with vasculopathy and autoantibody production. "CD99 contributes to the pathogenesis of systemic lupus erythematosus (SLE)." (PMID 32959501, 2020).
thyroid tumour (1 paper, 2025). "The observed discrepancies in CD99 and CD6 binding in APOE‐low thyroid tumour cells contribute to oncogenic functions, although the underlying mechanisms require further investigation." (PMID 39810624, 2025). "With the advantage of an integrated spatial transcriptome, we also discovered that thyroid tumour cells with low APOE expression interacted with DCs and CD4+ T cells via CD99‐regulated signalling but minimally interacted with the CD6 receptor." (PMID 39810624, 2025).
tuberculosis (1 paper, 2024). A chronic, recurrent infection caused by the bacterium Mycobacterium tuberculosis. "Here, we focus on the main signaling pathways involved in the fibroblast formation in the core area of tuberculosis, such as THBS, CD99, MIF, COMPLENENT, CXCL, THY1, and GAS pathways." (PMID 39431015, 2024).
urothelial carcinoma (1 paper, 2012). A malignant neoplasm derived from the transitional epithelium of the urinary tract (urinary bladder, ureter, urethra, or renal pelvis). "The urothelial carcinoma component within the ureter, the tumor cells were positive for cytokeratin, epithelial membrane antigen, E-Cadherin and negative for Vimentin, S-100 and CD99, enhancing the contrast of synchronous urothelial carcinoma from mesenchymal chondrosarcoma." (PMID 22999069, 2012).